U8 (U8 small nucleolar RNA )
Synonyms: LOC124900552
Gene: Small nucleolar RNA gene on chromosome 3 (154,007,367 to 154,007,502, reverse strand). Ensembl gene ENSG00000201398.
Gene Ontology:
Biological process: RNA processing
Cellular component: nucleolus
Homologues: Orthologues: chimpanzee U8 (99% identical), macaque U8 (90% identical). Paralogues in human: U8 (79% identical), U8 (78% identical), U8 (77% identical), U8 (76% identical), U8 (74% identical), U8 (73% identical), U8 (71% identical), U8 (70% identical), U8 (69% identical), U8 (68% identical), U8 (64% identical), U8 (60% identical), and 1 more.